APOB (apolipoprotein B)
Diseases named in the same sentence as APOB in open-access papers (continued):
Sharing a sentence is not in itself a finding about the gene and the disease.
intestinal diseases (2 papers, 2022 to 2025). "Recent studies are mainly limited to diseases such as those mediated by the apoB gene or its regulatory region mutation-related hypolipidemia, and few have focused on intestinal diseases." (PMID 36371157, 2022).
respiratory disease (1 paper, 2018). "The connection of apolipoprotein B (encoded by gene APOB) with respiratory disease has already been suggested in the literature." (PMID 29751582, 2018).
APOB also shares sentences with these, for which no sentence is quoted: acute myocardial infarction (18 papers); end-stage renal disease (7); essential hypertension (7); hypoalphalipoproteinemia (6); Venous thrombosis (6); metabolism (5); coronary artery (4); hepatitis C (4); inflammation (4); small vessel stroke (4); cryptogenic cirrhosis (3); fetal growth restriction (3); gallbladder cancer (3); hyperchylomicronemia (3); hyperhomocysteinemia (3); hyperlipemia (3); Osteopenia (3); venous thromboembolism (3); alcoholic liver diseases (2); arrhythmogenic right ventricular cardiomyopathy (2); brain injuries (2); cardiac arrest (2); colitis (2); Crohn disease (2); endometrial carcinoma (2); esophageal cancer (2); Failure to thrive (2); glaucoma (2); HBOC syndrome (2); Hypoalbuminemia (2).
A further 168 diseases each share a sentence with APOB in 2 papers or fewer.